RNU6-1246P (RNA, U6 small nuclear 1246, pseudogene)
Gene: Small nuclear RNA gene on chromosome 1 (72,717,663 to 72,717,769, reverse strand). Ensembl gene ENSG00000212366.
Homologues: Orthologues: chimpanzee U6 (100% identical), macaque U6 (92% identical). Paralogues in human: RNU6-166P (82% identical), RNU6-1024P (81% identical), RNU6-259P (81% identical), RNU6-266P (81% identical), RNU6-41P (81% identical), RNU6-558P (81% identical), RNU6-1060P (80% identical), RNU6-1152P (80% identical), RNU6-1181P (80% identical), RNU6-132P (80% identical), RNU6-142P (80% identical), RNU6-15P (80% identical), and 1285 more.